CD4 (CD4 molecule)
Diseases named in the same sentence as CD4 in open-access papers (continued):
Sharing a sentence is not in itself a finding about the gene and the disease.
Obesity (continued). "In murine models of obesity, liraglutide could effectively change the CD4 + T‐cell subsets and the cytokines, leading to an increase in Th2 and Treg and a concomitant reduction in Th1 and Th17 cells." (PMID 40838278, 2025). "Lymphatic dysfunction secondary to diet-induced obesity involves chronic inflammation, such as peri-lymphatic accumulation of macrophages and CD4+ T cells, and the consequences of hyperglycemia and insulin resistance, including decreased pumping capacity and increased lymphatic leakiness." (PMID 40821816, 2025). "This section discusses the CD4+ subsets in the context of obesity, T2D, and related comorbidities." (PMID 40838278, 2025). "The reduction of CD4− iNKT cells in the peripheral blood of individuals with obesity could result from several mechanisms: increased apoptosis, tissue infiltration, or impaired thymic development." (PMID 41000378, 2025). "FFC-fed CD4−/− mice developed the same level of obesity as FFC-fed WT mice." (PMID 40631180, 2025). "Interestingly, obesity significantly disrupted the distribution of iNKT cells between both subsets, leading to a fall in the percentage of CD4− subpopulation in favor to the CD4+ subset." (PMID 41000378, 2025). "Notably, CD4+ TCM were significantly elevated in MUO, supporting their involvement in obesity-associated inflammation, insulin resistance, and type 2 diabetes." (PMID 40244276, 2025). "Consequently, the distribution of these subsets shifted with an increased proportion of CD4+ iNKT cells, at the expense of CD4− iNKT cells, in individuals with obesity." (PMID 41000378, 2025). "The inverse association between obesity and LTBI was more evident among participants with CD4 counts < 500 cells/μL, suggesting that the relationship may vary with the level of immunosuppression." (PMID 41305316, 2025). "Additionally, adipocyte-MHC-II expression has been reported to participate in the regulation of CD4+ T cells in obesity." (PMID 38566998, 2024). "Although VAT-derived PD-1+CD4 Tconv cells demonstrate a polyclonal constitution in the context of obesity, we sought to elucidate whether the presence of dysglycemia engenders a distinctive profile in the TCRβ repertoire." (PMID 38380252, 2024). "While leptin, an adipocyte-derived hormone/cytokine that primarily regulates food intake and basal metabolism, is crucial for glucose uptake in effector T cells, chronic systemic leptin secretion in obesity can disrupt CD4+ T cell differentiation and lead to poor T cell responses." (PMID 39469362, 2024). "In addition, immunophenotyping revealed the increase of the surface expressions of CD44 and CD69 on various cell types, such as CD8+ and CD4 + T-cells, B-cells and macrophages, in animals with obesity." (PMID 39004641, 2024). "One immune cell trait, effector memory CD4+ T cell absolute count (WHR, WHRadjBMI), may reduce the risk of obesity." (PMID 38558794, 2024). "In similarity to T17-like cells, T1/17-like CD4+CD8+ Tf cells were also reduced in participants with Class III obesity (nOB: 10 ± 9.1, OBII: 13% ± 7.7, OBIII: 6.9% ± 5.1, OBIV: 12% ± 5.4; OBIII vs. OBIV, p < 0.05) and in the IRn group (6.8% ± 5.7, p > 0.05 vs. nOB)." (PMID 38397455, 2024). "However, a decrease in T1/17-like CD4+CD8+ T cells was observed in Class II obesity (p < 0.05 vs. nOB)." (PMID 38397455, 2024). "Inflammation may also play a part stimulating adipogenesis, e.g. T-cell inhibition/depletion of CD4+ cells decrease the severity of lymphoedema in animals with obesity." (PMID 38961152, 2024). "As PD-1 can mark antigen-specific T cells and clonality of VAT-derived T cells has been described in preclinical models of obesity, we wondered whether PD-1+CD4 Tconv cells undergo clonal expansion toward specific antigens in the VAT of OB-Dys." (PMID 38380252, 2024). "Importantly, almost 31% of the CD4+ Tregs in circulation, from people with obesity, showed a Tfr phenotype, while 29% presented a Th1/Th17-like phenotype." (PMID 38397455, 2024).
Obesity (continued). "Interestingly, obesity-induced T cell contraction of both CD4+ and CD8+ T cells was significantly more pronounced in males, whereas female OD mice displayed widely preserved numbers of circulating and splenic T cells." (PMID 39125804, 2024). "It is speculated that CD4+ T cells can store the body’s obesity memory, mediate obesity, and promote weight recovery, making it difficult to lose weight, and maintain weight after weight loss, and therefore induce weight cycling." (PMID 38921478, 2024). "Interestingly, the higher the BMI, the lower the CD4+ Treg percentage, with Class IV obesity showing the lowest value (nOB: 0.89% ± 0.3; II: 0.69 ± 0.36; III: 0.70 ± 0.27; IV: 0.63% ± 0.9; nOB vs. IV, p < 0.05)." (PMID 38397455, 2024). "However, to our knowledge, we are the first to describe sex-specific differences in obesity-induced dysregulation of circulating lymphocyte subpopulations, e.g., CD4+ and CD8+ T cells." (PMID 39125804, 2024). "Furthermore, obesity Class II patients also had higher percentage of TIM-3+ Th1-like CD4+Tfr cells (11% ± 4.6) compared to nOB (p < 0.05)." (PMID 38397455, 2024). "Some controversy remains regarding the circulating CD4+ Treg cells in people with obesity." (PMID 38397455, 2024). "Notably, the proportional characteristics of immune cells observed in our patients without SF loss were similar to the results of previous studies that reported an increased CD8/CD4 ratio and favored the M1 over the M2 macrophage subtype in obesity." (PMID 36835404, 2023). "It has been reported that in obesity there is an increased frequency of pro-inflammatory CD4+ T cells (e.g., Th1 and Th17 cells), and cytotoxic CD8+ T cells, and reduction in anti-inflammatory CD4+ T cells (e.g., Th2 cells) and FOXp3 regulatory T cells (Tregs)." (PMID 37720534, 2023). "In the present study, we aimed to investigate the ability of obesity-related concentrations of leptin to modulate the in vitro effector and regulatory Fel d1-specific CD4+ T-cell subsets in patients allergic to cat, considered the third most common cause of respiratory allergy in humans." (PMID 37954580, 2023). "At the 3rd FU after LVAD implantation, CD4+ T cells of obese patients (62.4 ± 9.0%) remained above this range and significantly differed in comparison to pre-obese patients (52.7 ± 10.0%, ppre-obesity vs. obesity = 0.05)." (PMID 37885885, 2023). "Additionally, the ratio of CD8+ to CD4+ T-cells have been shown to increase with obesity, limiting the secretion of anti-inflammatory cytokines that inhibit macrophage migration from CD4+ regulatory T-cells." (PMID 37372149, 2023). "Obesity decreases the population of CD4+ T cells which play a critical role in NAFLD-HCC progression and loss of hepatic CD4+ T cells compromises immunotherapies, such as RNA vaccine (M30) and anti-OX40 antibody-mediated therapy against tumor cell growth in the liver." (PMID 37361533, 2023). "The suppression of CD4+ T regulatory cells (CD4+ Tregs) occurs in obesity as well." (PMID 38137918, 2023). "Notably, in patients with obesity, adiponectin can regulate the activity of pro-inflammatory CD4+ T cells, and its effectiveness in treating obesity has been demonstrated." (PMID 37266437, 2023). "Therefore, the main objective of the present study was to investigate the ability of obesity-related leptin doses to modulate the in vitro different effector and regulatory Fel d1-specific CD4+ T cells from patients with persistent cat allergies." (PMID 37954580, 2023). "The previous evidence showed that overweight and obesity statuses could either increase or decrease total lymphocytes and CD4+ T cells, the key players of adaptive immune system, in peripheral blood populations." (PMID 37833325, 2023). "Therefore, any adverse event that favors Th2/TFH cell expansion and damages regulatory CD4+ T cell phenotypes should affect the severity of atopic diseases, such as obesity." (PMID 37954580, 2023).
Obesity (continued). "Th17 cells characterize a subclass of CD4+ T cells that can produce interleukin-17 (IL-17), which plays a role on body weight control, adipocyte differentiation, insulin and glucose homeostasis, and low-grade sustained inflammation related to obesity." (PMID 36845826, 2023). "As the TBF percentage (severity of obesity) increases, CD4+, CD4+CD62-, and CD8+CD45RO+ T lymphocytes increase in peripheral blood, demonstrating the existence of an inflammatory process at the peripheral level that is also associated with other variables such as WC, BMI, CRP, leukocytes, and age." (PMID 37334132, 2023). "In addition, CD4+T cells in visceral adipose tissue have also been demonstrated to regulate insulin resistance and control glucose homeostasis in diet-induced obesity progression." (PMID 36776877, 2023). "Obesity correlates with the severity of inflammation, which is controlled mostly by CD4+ T lymphocytes; therefore, there is an increase in IL-6 secretion, which makes CD4+ cells differentiate to Th17." (PMID 36364955, 2022). "In severe obesity, the Treg cell population is reduced to 10% to 20% of the CD4 T-cell compartment." (PMID 36685567, 2022). "CD4+ Treg cells act to dampen immune responses, promote an anti-inflammatory environment and are likely protective against pathologic progression, as subsets of these cells are enriched in lean mice but lost with obesity and insulin resistance." (PMID 35399946, 2022). "The obesity-associated transformation of CD4 T cells remains a negative legacy even after weight loss, causing treatment resistance of obesity-related conditions." (PMID 36685567, 2022). "In recent studies performed in a mouse model of obesity, activated CD4+ T cells from diet induced obese mice had an altered metabolic profile characterized by increased glucose uptake, increased conversion of glucose to pyruvate, and increased mitochondrial oxidation." (PMID 36275776, 2022). "First, we hypothesized that immune dysfunction of CD4+ T cells accelerates tumor growth due to HFD-induced obesity." (PMID 36611881, 2022). "In a mouse model of obesity-induced insulin resistance, the percentages of CD4+FoxP3+ Treg cells and NEU1 levels were decreased, while the percentages of CD4+Th17+ cells and the levels of the NEU1-targeting microRNA, miR-23b-3p, were increased, all compared with nonobese controls." (PMID 35479093, 2022). "Normally, the placenta helps skew the maternal and fetal environment toward a CD4+ helper T cell type-2 (Th2) and anti-inflammatory profile; however obesity and other stresses create a more CD4+ helper T cell type-1 (Th1) and inflammatory gestational environment." (PMID 35573953, 2022). "Interestingly, the obesity‐related leptin dose not only elevated Th2 and Th17 cytokine levels, but also directly reduced the Treg function in CD4+ T cell cultures from lean AA patients." (PMID 35734271, 2022). "Moreover, treatment with live PD in mice was shown to have anti-inflammatory effects, reduce weight gain, improve glucose homeostasis, correct obesity-related abnormalities, and induce regulatory T lymphocytes from naïve CD4+ T cells." (PMID 35085328, 2022). "Our findings of the impact of HFD-induced obesity on the anti-tumor activity of CD4+ T cells may provide a clue to elucidate the pathogenesis of poor outcomes of CRC with obesity comorbidities." (PMID 36611881, 2022). "CD4+ T cells regulate inflammation in adipose tissue and obesity." (PMID 36031641, 2022). "Within obese adipose tissue, increased expression of TNFα has been shown to reduce CD4+ T cell function, suggesting that obesity may also inhibit the function of CD4+ T cells early during breast tumorigenesis." (PMID 35435599, 2022). "Also, obesity‐related leptin level not only decreased IL‐10 production by CD4+ T cells, but also reduced the in vitro suppressive function of these lymphocytes from lean and obese AA patients." (PMID 35734271, 2022).
Obesity (continued). "illustrated that CCR5 deficiency exacerbated glucose tolerance and increased CD4+ T cells but not macrophage infiltration into adipose tissue in obesity." (PMID 36713454, 2022). "When obesity persists, prolonged stimulation by leptin and circulating free fatty acids, repetitive antigen stimulation, activating stress responses, and hypoxia induce exhaustion of CD4 T cells in VAT." (PMID 36685567, 2022). "Furthermore, KLHL29 had good AUCs and a close relation to CD8 T cells, CD4 naive T cells, gamma delta (γδ) T cells, and M2 macrophages in our study, which indicated that KLHL29 had a potential association with obesity and DCM, especially immunologically." (PMID 36547458, 2022). "Interestingly, obesity‐related leptin concentration significantly increased the ability of purified CD4+ T cells from lean AA patients to produce IL‐5, IL‐13, IL‐17 and IL‐6, but diminished IL‐10 release." (PMID 35734271, 2022). "Although the molecular mechanism for this obesity memory is unknown, CD4 effector T cells were shown to be involved." (PMID 36685567, 2022). "In summary, our results indicated that obesity might increase AA severity by favoring the expansion of Th17‐like and Th2/Th17 cells and decreasing regulatory CD4+T cell subsets, being adverse effects probably mediated by leptin overproduction." (PMID 35734271, 2022). "Obesity is a chronic disease correlated with systemic inflammation, characterized by the presence of CD4 and CD8 T cell infiltration and modified immune response, which contributes to the development of obesity related diseases and metabolic disorders, including impaired glucose metabolism." (PMID 34199040, 2021). "Obesity is associated with elevated levels of the adipokine leptin, and epidemiological studies demonstrate that PLWH with higher circulating leptin levels have increased CD4+ T cell reconstitution compared to those with lower leptin levels." (PMID 35111163, 2021). "However, CD4+ T cells can contribute significantly to inflammation observed in obesity and obesity-related IR." (PMID 34557550, 2021). "In the presence of an inflammatory state, such as the obesity-dependent inflammation present in AT, different studies have observed an increase of circulating Th17 and Treg and a correlation with dysregulation of CD4+ subset." (PMID 34199040, 2021). "Furthermore, obesity gene markers were also upregulated in CD4+ T cells from obese asthmatics compared with the two other groups." (PMID 34576307, 2021). "Moreover, ablation of AP function in DCs suppressed the obesity-induced CD4+ T cell increment in VAT." (PMID 34445379, 2021). "Given the associations among vitamin D, obesity, and CD4+ T cells, it is worth examining whether the effects of vitamin D on CD4+ T cell subsets are influenced by obesity." (PMID 33670988, 2021). "In this study, the percentage of CD4+IL-17+ T cells tended to be higher and that of CD4+CD25+Foxp3+ T cells was higher in purified T cells from the HFD groups compared with the CON groups; however, the CD4+IL-17+ T cells/CD4+CD25+Foxp3+ T cells ratio was unaffected by obesity." (PMID 33670988, 2021). "Combined, these results demonstrate that obesity is associated with greater CD4+ T cell proliferation among PLWH, and that higher circulating leptin levels in obesity may contribute to improved CD4+ T reconstitution in PLWH initiating ART." (PMID 35111163, 2021). "Although the precise mechanistic explanations for the alteration in the number and population of CD4+ T cells seen with obesity remain unclear, mTOR activation by increased leptin may be involved." (PMID 33670988, 2021). "We then examined the functional capacity of CD44+CD4+ TILs, to determine whether obesity blunted their effector function in therapy-treated mice." (PMID 34064933, 2021).
Obesity (continued). "In our present study, we found that after the construction of obesity-induced IR animal model, in total CD4+ T cells, Treg cells were reduced, Th17 cells were increased, levels of markers TGF-β1 and IL-10 were downregulated, and those of IL-17 and IL-6 were upregulated." (PMID 33781239, 2021). "We next asked whether obesity was increasing the rates of cell death in CD44+CD4+ TILs from DIO mice, again focusing on the day 21 time point." (PMID 34064933, 2021). "Taken together, these results support the hypothesis that maternal pregravid obesity alters the development and epigenome of CD4 T cells in the offspring, providing a potential link to increased susceptibility to chronic inflammatory diseases and infection." (PMID 33912153, 2021). "Another study with same model, showed that CD11c+ cell ablation results in the reduction of CLS formation with increased Il10 and decreased Il6 and Mcp1 expression in VAT.These results indicate the crucial role of ATDCs to activate CD4+ T cells that contributes to AT inflammation in obesity." (PMID 34445379, 2021). "Numbers of VAT CD4+ T cells increase as adipose tissue expands in obesity." (PMID 34572084, 2021). "In addition, phenotypic switching of CD4+ T cells and recruitment of T cell and B cells precedes macrophage infiltration, and obesity macrophage polarity skews to a more inflammatory phenotype." (PMID 33297933, 2020). "However, absence of MHCII antigen presentation molecules, which are critical for activation of antigen specific CD4+ T cells, protects against obesity-induced IR." (PMID 32973799, 2020). "Furthermore, the peripheral blood mononuclear cells from influenza vaccinated adults with obesity had less active CD4+ and CD8+ T cells with reduced marker expression of CD28, CD40 ligand, CD69, IL-12R, and IFN-γ." (PMID 32806722, 2020). "These hypertrophic adipocytes can function as APCs to activate CD4+ ART and instigate adipose tissue inflammation, which could cause many obesity-related medical complications." (PMID 33329579, 2020). "It is possible that this might occur via altered signalling within CD4 + T-cells, which aid in regulation of obesity-induced inflammation, and which can express gp130." (PMID 32603641, 2020). "Rag-deficient HFD-fed mice showed marked obesity and IR in comparison to their WT counterparts, a phenotype that was abrogated by the adoptive transfer of CD4+, but not CD8+ T cells." (PMID 33282920, 2020). "Here, we aim to determine whether specific phenotypic and functional properties of visceral adipose tissue (VAT)-derived CD4 conventional T cells (Tconv) and CD8 T cells are associated with dysglycemia in human obesity." (PMID 32299896, 2020). "As observed for CD8+ T cells, the effector functions of BM CD4+ T cells may be impaired with obesity, as reduced expression of activation/exhaustion marker PD-1 could be observed." (PMID 32514279, 2020). "In addition, obesity promotes the differentiation of Th17 cells by increasing the expression of lipid kinase in CD4 T cells." (PMID 32370746, 2020). "Given recent evidence of PD-L1 upregulation in obesity, we speculated that decreased CD4+ T cell numbers within the CNS of DIO mice with EAE may reflect upregulation of PD-L1 in CNS resident or infiltrating myeloid cells." (PMID 33193426, 2020). "This study demonstrates that abnormal undiagnosed CVD risk factors including obesity, hypertension, hypercholesterolemia, and DM were common and that HIV patients with CD4 count above 350 had higher odds of having more than one CVD risk factors compared to adult blood donors without HIV." (PMID 31571256, 2019). "However, there remains a critical gap in knowledge of how CD4+ T cells become skewed towards Th1 vs. Th17 subsets in adipose tissue and how this changes as obesity is established." (PMID 31015794, 2019). "Furthermore, intestinal adaptive immunity, including CD4+ T cells, affects metabolic regulation in obesity." (PMID 31756626, 2019).